E2F1 (E2F transcription factor 1)
Diseases named in the same sentence as E2F1 in open-access papers (continued):
Sharing a sentence is not in itself a finding about the gene and the disease.
breast tumors (26 papers, 2006 to 2024). "For example, in some breast tumors, there is a loss of E2F1 expression and that of its targets, such as EBP1 and apoptosis-inducing genes." (PMID 21085677, 2010). "E2F1 is linked to HER2 signaling and trastuzumab actions, with research showing its involvement in proliferative breast tumors." (PMID 38534787, 2024). "We integrate gene expression profiles of cancer cell lines from two E2F1-driven highly aggressive bladder and breast tumors, and use network analysis methods to identify the tumor type-specific core of the network." (PMID 28775339, 2017). "To further substantiate these findings, we examined the effects of E2F1 activity on the invasive capacity of patient-derived metastatic bladder and breast tumor cell lines using functional invasion assays, western blotting, and PCR analysis." (PMID 28775339, 2017). "Although in cell lines we found that E2F1 induction reduces TPIP expression, in breast tumors there was a positive correlation between E2F1 and TPIP expression levels." (PMID 26230935, 2015). "H19 also enhanced the G1-S transition via binding to the E2F1 in breast tumor cells." (PMID 36597150, 2023). "To determine which E2F transcription factors could be associated with upregulation of FA genes, we studied also the mRNA expression levels of activating E2F genes (E2F1, E2F2, E2F3) in RB1-mutated retinoblastoma and in basal breast tumors." (PMID 25161863, 2014). "This indicates that high E2F1 levels reduce the response of breast tumors to therapy." (PMID 24330704, 2013). "Moreover, in TCGA breast tumors, the predicted E2F1 transcription factor activity, inferred from the tumor sample’s protein expression profile using a trained affinity regression model, positively correlates with CENPI mRNA level in the tumors (r=0.5186, p<0.0001, Spearman correlation)." (PMID 28977935, 2017). "Analysis of TCGA RNA sequencing data through the UALCAN platform revealed that the expression of ATAD2, E2F1, and FOXM1 were all significantly higher in primary breast tumor samples when compared to normal samples." (PMID 39335162, 2024). "MALAT1 increased breast tumor cell proliferation by miR-124 sponging and activating the CDK4/E2F1 axis." (PMID 36597150, 2023). "The expression of ABHD11, ADORA2B, E2F1, EZH2, PAICS, SFN and SH3GL1 was significantly higher in grade III than in grade I breast tumors." (PMID 28411283, 2017). "Specifically, all three over-expressed key regulators in breast tumors, GATA3, E2F1 and RAD21, showed connection with these two lincRNAs." (PMID 27897201, 2016). "In breast tumors, expression analysis of RAD51/TODRA, E2F1 and TPIP shows perturbed regulation of RAD51 expression, and the associated increase in RAD51 expression correlates with an aggressive tumor phenotype." (PMID 26230935, 2015). "Also, E2F1, E2F2, E2F3, Mps1/TTK, BubR1, NDC80 (HEC1), Nek2, and Sgo1 significantly co-overexpress in breast tumors." (PMID 29100415, 2017). "Notably, similar to ESRP1, E2F1 also gets upregulated in the primary breast tumor as opposed to normal breast tissues." (PMID 34362878, 2021). "RAD51 expression in breast tumors was positively correlated with E2F1 expression and negatively correlated with TODRA, indicating that E2F1 indeed regulates the bidirectional promoter in vivo in the malignant state, in the same manner we observed in cell lines." (PMID 26230935, 2015).
breast tumors (continued). "Therefore, the E2F-1/TatHA proteins investigated in this study would be potential adjuvants to therapy in nonmetastatic, primary breast tumors." (PMID 18366791, 2008). "Observations that E2F1, E2F2, and E2F3 correlate with relapse-free but not overall survival was confirmed by mining the METABRIC database, a database that encompasses over 2000 breast tumors, with cBioPortal." (PMID 29100415, 2017).
triple-negative breast carcinoma (24 papers, 2014 to 2026). An invasive breast carcinoma which is negative for expression of estrogen receptor (ER), progesterone receptor (PR), and human epidermal growth factor receptor 2 (HER2). "It has been demonstrated that overexpression of E2F1 in triple-negative breast cancer (TNBC) cell line MDA-MB-468 induces apoptosis; however, a mechanism for this observation has not been determined." (PMID 41596544, 2026). "E2F1 activity in triple-negative breast cancer patients is clinically relevant, as one study showed that patients that respond to doxorubicin treatment had upregulated E2F1 in tumor biopsies and non-responders did not." (PMID 41596544, 2026). "In triple-negative breast cancer, E2F1 and EIF4A3 promoted high expression of circRNA circSEPT9, which in turn promoted cell proliferation, invasion, tumorigenesis, and metastasis in vivo." (PMID 37322413, 2023). "For example, in triple-negative breast cancer, Anp32e is known to enhance the expression of transcription factor E2F1 and induce tumorigenesis." (PMID 36263179, 2022). "The expression of circRNAs can be regulated by transcription factors; for example, circSEPT9 expression in triple-negative breast cancer cells is mediated by E2F1 and EIF4A3." (PMID 36072902, 2022). "ANP32E has the potency to induce the tumor formation capacity of triple-negative breast cancer cells by transcriptionally potentiating E2F1." (PMID 34551785, 2021). "The literature reports that circRNA circSEPT9 could promote the proliferation and invasiveness of triple-negative breast cancer cells by enhancing E2F1 expression." (PMID 35030974, 2022). "In addition, ANP32E promotes the development of triple-negative breast cancer via transcriptionally activating E2F1." (PMID 33148205, 2020). "In summary, we have demonstrated some of the effects of CDK8 inhibition on CDK8, E2F1, STAT3, and Mcl-1 proteins in MDA-MB-468 triple-negative breast cancer cells." (PMID 41596544, 2026). "We continue to investigate the contributions of E2F1 and STAT3 to CDK8 inhibitor effects on triple-negative breast cancer cell line MDA-MB-468, and will report our results in due course." (PMID 41596544, 2026). "The circRNA circSEPT9 mediated by E2F1 and EIF4A3 facilitates the carcinogenesis and development of triple-negative breast cancer." (PMID 37410095, 2023). "Knockdown of ZNF703 in triple-negative breast cancer cells was shown to inhibit the expression of cyclin D1, CDK4, CDK6, and E2F1 and upregulation of Rb1." (PMID 37686244, 2023). "In triple-negative breast cancer, ANP32E can promote E2F1 transcription to promote G1/S transformation of TNBC cells, thereby inducing tumorigenesis." (PMID 35280441, 2022). "Our data reveal that the circSEPT9 mediated by E2F1 and EIF4A3 facilitates the carcinogenesis and development of triple-negative breast cancer through circSEPT9/miR-637/LIF axis." (PMID 32264877, 2020). "In a similar context, ANP32E is found to induce oncogenesis of triple-negative breast cancer (TNBC) by upregulation of the transcription factor, E2F1." (PMID 32605309, 2020). "Additionally, circSEPT9 mediated by E2F1 and EIF4A3 propels the carcinogenesis and progression of triple-negative breast cancer via the circSEPT9/miR-637/LIF axis." (PMID 38956466, 2024). "For example, circSEPT9 regulated by E2F transcription factor 1 (E2F1) and eukaryotic translation initiation factor 4A3 (EIF4A3) pushes the cancerous derivation of triple-negative breast cancer through the circSEPT9/miR-637/Leukemia Inhibitory Factor (LIF) axis." (PMID 34540684, 2021). "For instance, it was recently found that E2F1 and EIF4A3 might promote the biogenesis of circSEPT9 and the occurrence and development of triple-negative breast cancer by acting on the miR-637/LIF axis." (PMID 33323543, 2020). "HER2(+) and triple negative breast cancer was strongly associated with HOXB9 staining, but not with E2F1 reactivity." (PMID 25136922, 2014).
retinoblastoma (20 papers, 2007 to 2025). A malignant tumor that originates in the nuclear layer of the retina. "This work demonstrates that Pten deletion, activation of the PI3K/AKT pathway, or suppression of FOXO activity eliminates cell death caused by E2F1 in vivo in the retina and also induces rapid, bilateral retinoblastoma emergence." (PMID 25907958, 2015). "In RB1-mutated retinoblastoma, all three activating E2Fs were significantly upregulated: E2F1 (FC = 1.86, P = 2.56E-03), E2F2 (FC = 2.84, P = 2.31E-04), and E2F3 (FC = 3.72, P = 2.18E-10)." (PMID 25161863, 2014). "Previous studies have shown that loss of E2f1 rescues retinal differentiation and retinoblastoma formation, in Rb-deficient mice." (PMID 25338120, 2014). "Targeting dysregulated E2F1 activity emerges as a crucial therapeutic strategy to inhibit cell proliferation and induce apoptosis in retinoblastoma cells." (PMID 39000021, 2024). "The high UHRF1 expression was accompanied by a high level of E2F1 expression which was also observed in retinoblastoma by others." (PMID 28467809, 2017). "In our mouse retinoblastoma model, an E2F1/FOXO pro-apoptotic transcriptional complex, which is active following disruption of RB and p107, induces widespread apoptosis that results in loss of most of the retinal." (PMID 28445155, 2017). "When combined, our analyses of these 9 strains of mice suggest that E2f1 is unique in its ability to rescue both retinoblastoma formation in the 7D model and the retinal development phenotype in the Rb cKO model." (PMID 25338120, 2014). "In pediatric retinoblastoma, E2F1 could increase the expression of CKS2 via binding to its promotor, thereby promoting the promotes cell proliferation and tumor formation." (PMID 40070576, 2025). "To confirm that E2F1 did play a causal role in promoting transcription of CKS2, we knocked down E2F1 with two short hairpin RNAs (shRNAs) in human retinoblastoma cells (Y79 and WERI-Rb-1) and found that expression of CKS2 was significantly decreased in both RNA and protein levels." (PMID 36096885, 2022). "This study discovered E2F1/CKS2/PTEN signaling axis regulates malignant phenotypes in pediatric retinoblastoma, and CKS2 may serve as a potential therapeutic target for this disease." (PMID 36096885, 2022). "Activity of Cdk2/Cyclin E is essential for phosphorylation of Retinoblastoma and release of E2F1." (PMID 34520549, 2021). "However, aE2Fs are essential for abnormal division of differentiating RB-null cells and removing E2F1 or E2F3 completely block retinoblastoma formation." (PMID 32071286, 2020). "Previous studies have shown that loss of E2f1 and E2f3, but not E2f5, prevents retinoblastoma formation in Rb1-deficient mice." (PMID 30220967, 2018). "This suggests that “normal” levels of AKT activity is insufficient to offset the strong pro-apoptotic stimulus from deregulated E2F1 following loss of both Rb and p107 in mice, which do not develop retinoblastoma from Rb deficiency alone." (PMID 28445155, 2017). "We evaluated whether E2F1 requires FOXO1 to induce pro-apoptotic target gene expression in Y79 human retinoblastoma cells transfected separately with control or two FoxO1 siRNAs." (PMID 25907958, 2015). "E2F1 induces apoptosis and acts as a tumor suppressor in retinoblastoma." (PMID 25004126, 2014). "Also, our results support a role of E2f1 and E2f3 in retinoblastoma formation through deregulation of miRNA expression." (PMID 25338120, 2014). "Indeed, several studies identified UHRF1 as a direct target of E2F1 in various cell systems, and genetic disruption of E2f1 or E2f3 in a murine retinoblastoma model was shown to ablate UHRF1 expression in Rb1-knockout retinae that would otherwise exhibit high UHRF1 expression." (PMID 28467809, 2017). "This is strengthened by the observation that the mRNAs for E2F1 and E2F2, cyclins A1, A2 and cyclins E1 and E2 as well as the mRNAs for the ribonucleotide synthase subunits RRM1 and RRM2 are high in retinoblastoma primary tumors." (PMID 38332874, 2024).
retinoblastoma (continued). "A previous study performed in retinoblastoma, a childhood cancer caused by bi-allelic loss of RB1, indicated that retinal tumorigenesis was driven by E2F1- and E2F3-transcribed genes following the lack of transcriptional repression due to RB loss." (PMID 30220967, 2018). "Eight E2F family members have been identified so far, E2F1 to E2F8, whereas E2F1 to E2F6 share the same structure: conserved DNA binding and dimerization domains, and, except for E2F6, have domains for transactivation and binding Pocket Proteins (PP): p107, p130 and Rb (Retinoblastoma)." (PMID 21637599, 2010). "E2f1, rather than other E2fs, may be a potential target for novel therapeutics to prevent retinoblastoma in RB1+/− humans." (PMID 17608565, 2007). "By screening a set of cancer-related genes directly regulated by transcription factor E2F1 and a series of experimental validations, we demonstrated that E2F1/CKS2/PTEN signaling axis regulates malignant phenotypes in RB and CKS2 may serve as a potential therapeutic target for retinoblastoma." (PMID 36096885, 2022).
endometrial cancer (19 papers, 2013 to 2025). Primary or metastatic malignant neoplasm involving the endometrium (mucous membrane that lines the endometrial cavity). "In endometrial cancer, the positive expression of E2F1 in cancer tissues is significantly higher than that in normal endometrial tissues, and the expression is related to tumor grade and stage." (PMID 35833075, 2022). "The expression of E2F1/2/3/7/8 was significantly upregulated in endometrial cancer tissues, converse to E2F4, which was downregulated." (PMID 33329696, 2020). "This strong association of expression of E2F1, E2F2 and MYBL2 with ATAD2 is found in both CAHs, primary and metastatic endometrial cancer lesions, indicating that the expression of these genes are tightly linked in all stages of endometrial cancer." (PMID 26308378, 2015). "We found that ATAD2 copy-number, ESR1 expression and E2F1 expression explained 77% of the variation in ATAD2 expression in endometrial cancer, and each of the predictor variables remained significantly associated with ATAD2 expression in the adjusted model." (PMID 23393560, 2013). "E2F8, E2F7, and E2F1 were the top three, most-frequently altered genes in endometrial cancer." (PMID 33329696, 2020). "Furthermore, the effects on endometrial cancer cells were dependent upon the recruitment of p300 and E2F1 via lncRNA DLX6‐AS1." (PMID 32951317, 2020). "Moreover, MELK overexpression promotes endometrial carcinoma progression by modulating the E2F transcription factor 1 (E2F1) protein and activating the mTORC1 (mammalian transducer of regulated cAMP response element-binding protein) and mTORC2 signaling pathways." (PMID 38848146, 2024). "Some of these genes, such as CDKN2A, E2F1, and ERBB2, have been characterized in endometrial cancer tumorigenesis." (PMID 35205261, 2022). "In 2015, a study observed that the expressions of E2F transcription factor 1 (E2F1), E2F transcription factor 2 (E2F2), and MYB proto-oncogene like 2 (MYBL2) are closely associated with ATAD2, which may be related to the invasion and progression of endometrial cancer." (PMID 36479043, 2022). "In cervical cancerous cells, concentrations of p16, E2F1, p107, and p130 increase as a result of applying AMH, while in endometrial cancer, these are concentrations of p107 and p130." (PMID 33080800, 2020). "In endometrial cancer cell lines (AN3CA) lacking p16 and pRb, MIS-induced apoptosis was associated with an increase in p107 and p130 and a decrease in E2F1 expression at 72 h." (PMID 25760378, 2015). "Interrogating Uterine Corpus Endometrial Carcinoma (TCGA-UCEC) and Uterine Carcinosarcoma (TCGA-UCS) cohorts revealed NCL to be the most highly upregulated gene in carcinosarcoma, with S100A11, LMNB2, RERG, E2F1 and CCNA2 representing key dysregulated NAGs in EC." (PMID 35682908, 2022). "This same pattern is also observed for E2F1 and MYBL2, located close to the region 20q13 often amplified in the serous like molecular sub group of endometrial cancer, indicating that in addition to a transcriptional link, these genes may also be co-amplified due to general genomic instability." (PMID 26308378, 2015).